GSK3B (glycogen synthase kinase 3 beta)
Diseases named in the same sentence as GSK3B in open-access papers (continued):
Sharing a sentence is not in itself a finding about the gene and the disease.
leukemia (continued). "Additionally, circ_0121582 exerted a repressive effect on leukemia growth by promotion of GSK3β expression through sponging miR-224 and direct binding to ten-eleven translocation 1 (TET1)." (PMID 37124518, 2023). "In leukemia stem cells, GSK3β controls survival, proliferation and differentiation." (PMID 33498808, 2021). "GSK3β has been found activated in many cancers, among them leukemia." (PMID 33498808, 2021). "According to the authors of this data set37, embryonic stem cells were cultured in three different conditions: lif (serum media that has leukemia inhibitory factor), 2i (basal media that has GSK3β and Mek1/2 inhibitor), and a2i (alternative 2i that has GSK3β and Src inhibitor)." (PMID 33589635, 2021). "Despite the concerns about putative tumor suppressor functions for GSK3β as outlined in the previous section, early phase clinical trials for solid cancer and leukemia have tested synthetic pharmacological GSK3β inhibitors, lithium and approved medicines with the ability to inhibit GSK3β." (PMID 32503133, 2020). "Importantly, several proteins implicated in leukemia pathobiology emerged amongst the novel PPP3CA interactors such as Rb, NPM1, BCL11b, GSK3β and KDM1 (also known as LSD1)." (PMID 27304189, 2016). "First, we present a so far unknown regulation of PON2 protein expression through the Wnt/GSK3β/β-catenin pathway in leukemia and OSCC cells." (PMID 27322774, 2016). "Interestingly, several proteins implicated in leukemia pathobiology emerged amongst the novel PPP3CA interactors such as NPM1, BCL11b, GSK3β and KDM1 (also known as LSD1)." (PMID 27304189, 2016). "Indeed, our current studies demonstrate that GSK-3β mediates ER stress-induced lysosomal apoptosis in leukemia involving caspase-2-induced LMP and cathepsin B relocation, which result in caspase-8 and -3 activation." (PMID 26727221, 2016). "Furthermore, the suppression of β-catenin completely abolished the development of mixed lineage leukemia stem cells, reversed leukemia stem cells to a pre-leukemia stem-like stage, and induced a greater responsiveness to GSK3β inhibitors in vivo and in vitro." (PMID 24550888, 2014). "Inhibition of miR-1246 could up-regulate AXIN2 and GSK-3β and inactivate Wnt/β-catenin pathway, accompanied with inhibiting the expression of β-catenin and further influencing the expression of P-glycoprotein (P-gp) in the chemo-resistant leukemia cells." (PMID 34093820, 2021). "Additionally, previous work demonstrated that COR arrests the cancer cell cycle at the G1 phase in vitro via the PI3K/Akt pathway (Akt/GSK-3b/β-catenin/cyclinD1) in the leukemia cell line U937 and the CDKIs (p21/p27)/Cyclin(D1 and E) pathway in the leukemia cell line BCRC60176." (PMID 31207985, 2019). "treated leukemia U937 cells with cordycepin (an active ingredient of traditional medicine) alone or in combination with SB216763, a pharmacological inhibitor of GSK3‐β." (PMID 40576246, 2025). "The chemo-resistant properties of MDR leukaemia cells are diminished by the suppression of miR-1246, which modulates AXIN2 and GSK-3β, leading to the deactivation of the Wnt/β-catenin signalling pathway." (PMID 39679367, 2024). "In leukaemia cells, miR-1246 directly influences the 3′UTR seed-matching sites of AXIN2 and glycogen synthase kinase 3 beta (GSK-3β), worthwhile Wnt/β-catenin pathway participants." (PMID 39679367, 2024). "The resistant leukemia cell lines showed increased transcription levels of WNT/β‐catenin target genes DVL1, GSK3B, and FZD5." (PMID 36567628, 2023). "Based on these, we inferred that miR-1246 regulated the activity of Wnt/β-catenin pathway by targeting AXIN2 and GSK-3β and lastly took part in ADM resistance regulation of leukemia cells." (PMID 34093820, 2021).
leukemia (continued). "Based on this, we draw the following conclusions, miR-1246 influences chemo-sensitivity of leukemia cells via Wnt/β-catenin pathway by directly targeting AXIN2 and GSK-3β." (PMID 34093820, 2021). "JAM3 is highly enriched in leukemia-initiating cells and play an important role in the maintenance of leukemia-initiating cell stemness through LRP5/PDK1/AKT/GSK3β/β-catenin/CCND1 signaling pathways." (PMID 32979257, 2020). "Similarly, hyperactivation of PI3K/AKT signaling in mouse models by inactivation of downstream negative regulators such as Pten, Pml, GSK3β, and FoxO results in a transient increase in activated HSCs and has been reported to be accompanied by exhaustion, impaired repopulation capacity, or leukemia." (PMID 30446598, 2018). "Our finding of reduced GSK-3β expression in AML is consistent with greater inhibition by miR-26a-5p in MSC-derived exosomes compared to controls, however, studies in human leukemia are needed to gain more mechanistic insight." (PMID 28918518, 2017). "The diversity of pathways with which GSK-3β interacts (e.g. Wnt/β-catenin, PI3K/Akt, Ras/Raf/MEK/ERK and others), makes it a key therapeutic target for leukemia and other diseases." (PMID 27322774, 2016). "Strikingly, in mixed-lineage leukemia, activation of Wnt signaling was sufficient to (partially) revert anti-tumor effects of GSK-3β inhibition, and combined blockage of GSK-3β and β-catenin was required to achieve tumor regression." (PMID 25344861, 2014). "This is in line with published data showing that transient stabilization of MYC by inhibition of glycogen synthase kinase 3β (GSK-3β), which normally targets MYC for proteasomal degradation, sensitizes leukemia cells to chemotherapy leading to increased apoptotic cell death." (PMID 38184819, 2024). "So, the present work prospectively proved that miR-1246 could regulate chemo-resistant ability of leukemia cells via Wnt/β-catenin pathway by directly targeting AXIN2, GSK-3β and indirectly regulating P-gp expression." (PMID 34093820, 2021). "In agreement with this hypothesis, several of the genes identified in our analysis have been suggested to be putative therapeutic targets in leukemia, with either preclinical or clinical trials underway (CDK4, CDK6, GSK3b, MYC, LCK, NFkB2, BCL2L1, NOTCH1)." (PMID 21356087, 2011). "Interestingly, GSK3β is not a survival dependency gene in human leukemia cell lines, including OCI-AML2." (PMID 37036970, 2023). "Our data demonstrated for the first time the involvement of GSK-3β in pediatric ALL cells, and not in adult leukemia cells, although GSK-3β inhibition played a similar role in inducing apoptosis in leukemia cells via in vitro activation of NF-κB." (PMID 21110852, 2010).
myocardial infarction (56 papers, 2012 to 2025). Gross necrosis of the myocardium, as a result of interruption of the blood supply to the area, as in coronary thrombosis. "Conversely, cardiac-specific deficiency of GSK-3β significantly inhibited myocyte apoptosis after myocardial infarction (MI)." (PMID 28101515, 2016). "GSK-3β-specific deficiency dramatically inhibits apoptosis after myocardial infarction (MI), and conditional deletion of GSK-3α in the heart reduces the Bax/Bcl-2 ratio and apoptosis." (PMID 36036015, 2022). "The aim of this study was to investigate the effects of the GSK-3β/NF-κB pathway on integrin-associated protein (CD47) expression after myocardial infarction (MI) in rats." (PMID 34349643, 2021). "Some studies have confirmed that the PI3K/AKT/GSK3β pathway promotes fibrosis in myocardial tissues, and its upregulation damages cardiomyocytes and participates in the pathogenesis of acute myocardial infarction." (PMID 39590979, 2024). "The basic fibroblast growth factor activates Nrf2-triggered antioxidant defenses through Akt/GSK3β/Fyn signaling in myocardial infarction." (PMID 36248430, 2022). "A recent study showed that GSK-3β inhibition alleviated NLRP3 inflammasome activation in myocardial infarction, and subsequently affected IL-1β release." (PMID 36164369, 2022). "TTC and HE staining noted that compared with the GSK3β WT mice, GSK3β CKO mice showed a reduced myocardial infarction area, alleviated pathological changes in myocardial tissues, and decreased infiltration of necrotic cardiomyocytes and centrifugal cells." (PMID 35528516, 2022). "Naringin preconditioning can reduce myocardial I/R injury via regulatingmiR-126/GSK-3β/β-catenin signaling pathway, and this chemical can be used totreat acute myocardial infarction." (PMID 35416858, 2022). "FGF21 also protects the heart from ischemic–reperfusion injury and myocardial infarction by activating Akt-glycogen synthase kinase (GSK)-3β-caspase-3 dependent pathway." (PMID 30185439, 2018). "GSK3β inhibition also reduced myocardial infarct size (41 ± 2%) with HSP90 inhibition by radicicol or DSG partially inhibiting SB216763-induced infarct size reduction (54 ± 3%, 47 ± 1%, resp)." (PMID 26413502, 2015). "Recent studies have suggested that the PI3K/GSK3B/b-catenin signalling pathway shows potential anti-apoptotic effects after myocardial infarction (MI) in rat ischemic preconditioning or post-conditioning models." (PMID 26386043, 2015). "Notably, pharmacological GSK3β inhibition was shown to markedly improve myocardial dysfunction and prevent remodelling in a rat model of myocardial infarction through reducing NLRP3 inflammasome activation." (PMID 39392548, 2025). "Our study identified miR-199a-5p could promote the progression of myocardial fibrosis after myocardial infarction by targeting GSK-3β, which provides novel targets for diagnosis and treatment of MF." (PMID 36788811, 2023). "In antiheart failure, salidroside can inhibit the protein phosphorylation level of PI3K/AKT/GSK3β pathway and inhibit the protein expression of Col-I and profilin-I in heart failure rats after acute myocardial infarction (AMI), thus reducing the level of myocardial fibrosis and heart failure." (PMID 35265260, 2022). "Hinokitiol exerts cardioprotective effect through inhibition of GSK-3β and subsequent elimination of excessive autophagy, tuning autophagic activity in moderate extent for remedial profit in acute myocardial infarction and myocardial ischemia reperfusion injury." (PMID 35419165, 2022). "On the other hand, studies conducted on mice models suggest that N-terminal Ser9 phosphorylation of GSK-3β was neither changed, nor is associated with the reduced activity in the heart after pressure overload or myocardial infarction." (PMID 29504933, 2018).
myocardial infarction (continued). "Here we show that carbacyclin induces cardiomyocyte proliferation via a PPARδ/PDK1/p308Akt/GSK3β/β-catenin-pathway and that activated PPARδ signaling after myocardial infarction (MI) induces cardiomyocyte cell cycle activity and improves scarring as well as cardiac function." (PMID 28621328, 2017). "We found that inhibition of GSK3β may be a potential therapeutic intervention to reduce myocardial infarct and apoptosis in hypercholesterolemic subjects." (PMID 24124583, 2013). "We found that the GSK3β inhibitor SB216763 significantly improved heart pump function, reduced myocardial infarct size and apoptosis in hypercholesterolemic rats, which suggests that the downstream signal mechanisms of GSK3β in hypercholesterolemic myocardium is preserved." (PMID 24124583, 2013). "Additionally, a recent study in adult mouse heart demonstrated that cardiomyocyte specific deletion of glycogen synthase kinase (GSK)-3β following surgically induced myocardial infarction increased cardiomyocyte proliferation." (PMID 23300892, 2012). "In conclusion, our study identified miR-199a-5p could promote the progression of myocardial fibrosis after myocardial infarction by targeting GSK-3β, which plays an important role in the insulin signaling pathway, which provides novel targets for diagnosis and treatment of MF." (PMID 36788811, 2023). "The aim of this study was to elucidate the mechanism of beraprost sodium (BPS) in the intervention of myocardial fibrosis after myocardial infarction (MI) through glycogen synthase kinase‐3β (GSK‐3β) and to provide new ideas for intervention in myocardial fibrosis." (PMID 38018586, 2023). "GSK-3β inhibitors were found to exert cardioprotective effects in I/R injury, and these effects were attenuated by QCT, manifested by increased myocardial infarct size and release of lactate dehydrogenase and creatine kinase-MB." (PMID 32111033, 2020). "In isolated rat hearts, both NECA and the ERS inhibitor TUDCA decreased myocardial infarction, increased GSK-3β phosphorylation, and reversed GRP94 expression at reperfusion, suggesting that NECA protected the heart by inhibiting GSK-3β and ERS." (PMID 29391923, 2017). "To determine the role of the Arrb2/miR-155/GSK3β pathway in CSC-mediated cardiac repair in vivo, we injected stem cells from WT and KO mice into the hearts of mice with myocardial infarction." (PMID 24974728, 2014). "Of note, myocardial injury was independent of GSK3β pharmacological inhibitors and GSK3β levels in a mouse model of myocardial infarction highlighting differences in pathology between different heart diseases." (PMID 39392548, 2025). "Indeed, previous reports showed kallikrein gene transfer protected against acute phase myocardial infarction by promoting neovascularization and improving cardiac function by increasing AKT and GSK3β phosphorylation and thus reducing GSK3β activity." (PMID 29760720, 2018). "Our results were consistent with previous observations, where the total protein levels and Ser9 phosphorylation of GSK3β were not changed in the heart after pressure overload or myocardial infarction." (PMID 29504933, 2018). "While IPostC fails to decrease myocardial infarction in mice in which serine 9 within GSK3β is mutated to alanine (GSK3β-S9A mice), IPC and IPostC effectively reduce infarct size in mice in which serine 9 of GSK3β and serine 21 of GSK3α are rendered to non-phosphorylatable residues." (PMID 38674076, 2024). "We reported that conditional deletion of cardiomyocyte (CM)-GSK-3β protects against myocardial infarction (MI)-induced cardiac remodeling, with no role in Transverse Aortic Constriction (TAC)-induced pathological hypertrophy and cardiac dysfunction." (PMID 32365965, 2020).
myocardial infarction (continued). "Methods/Results: We used SRF small interfering RNA (siSRF), SRF small hairpin (shSRF) RNA sequence adenovirus, PI3K/Akt/GSK3β pathway inhibitors, t-AUCB, and 14,15-EEZE (a preparation of EETs antagonists) to treat mouse cardiomyocytes overexpressing miR-1 and mice with myocardial infarction (MI)." (PMID 34646152, 2021).
Obesity (53 papers, 2012 to 2026). Accumulation of substantial excess body fat. "We recently reported the critical role of cardiomyocyte (CM) Glycogen Synthase Kinase-3 beta (GSK-3β) in cardiac dysfunction associated with a developing obesity model (deletion of CM-GSK-3β prior to obesity)." (PMID 32365965, 2020). "DHA-rich fish oil supplementation significantly reduced the GSK-3β levels in individuals with obesity, a key kinase that is linked to the pathogenesis of T2D and AD." (PMID 32486256, 2020). "While these findings implicate a causal effect of GSK3β dysregulation in obesity-related hepatocarcinogenesis, the upstream kinase that controls GSK3β/mTORC1 signaling in the obesity-induced inflammatory microenvironment has not been elucidated." (PMID 30523261, 2018). "This study explores whether BBR regulates inositol requiring enzyme 1 (IRE1)/glycogen synthase kinase 3 beta (GSK-3β) axis to resist obesity-associated inflammation, thereby improving glucolipid metabolism disorders." (PMID 39791173, 2025). "The regulation of the PI3K/Akt/GSK-3β pathway may also be involved in the associations between obesity-induced inflammation and antidepressant responses." (PMID 26771598, 2016). "Hence, this study aims to explore whether BBR regulates the IRE1/GSK-3β axis to resist obesity-associated inflammation, thereby improving glucolipid metabolism disorders." (PMID 39791173, 2025). "Therefore, the regulation of Wnt/GSK-3β signaling might be a promising way for osteoporosis caused by obesity." (PMID 37447191, 2023). "The ability of anthocyanins to modulate GSK3β activity demonstrates their potential to support glucose and lipid metabolism, making them a valuable therapeutic tool for managing obesity and its related complications." (PMID 40218884, 2025). "In individuals with metabolic irregularities affecting obesity, GSK3B fosters NF-κB and CREB activation, prompting the expression of inflammatory factors in leukocytes." (PMID 40438591, 2025). "In contrast, the level of phosphorylated GSK3β was reduced (favouring GSK3β activation) in obesity-related and glucocorticoid-induced deterioration of bone health." (PMID 38672518, 2024). "AMPK activation is associated with inhibition of GSK3β, and JXGT-mediated activation of AMPK in our HFD-fed model also decreased the obesity-induced overexpression of GSK3β." (PMID 35382381, 2022). "AKT1, SRC, EGFR, and GSK3B were identified as key anti-obesity target genes of hispidulin, and estrogen, prolactin, Rap1, and PI3K-Akt signaling pathways were predicted to be involved in the anti-obesity effects of hispidulin." (PMID 34944408, 2021). "In the present study, we sought to determine the role of CM-GSK-3β in a clinically more relevant model where GSK-3β was deleted after establishing obesity." (PMID 32365965, 2020). "Congenital and acquired factors (e.g., genetic defects, gene mutations, obesity, and the environment) affect the IRS2/PI3K/AKT/GSK3β/GLUT4 pathway, causing IR." (PMID 32273844, 2020). "To determine the effect of GSK-3β deletion on cardiac function in an established obesity model, we performed two-dimensional echocardiography in WT and KO animals fed either a CD or HFD." (PMID 32365965, 2020). "Given the critical role of GSK3β, the direct substrate of CCRK24 on mTOR signaling in obesity-associated HCC20,22, it is conceivable that the CCRK/GSK3β cascade regulates mTORC1 signaling to promote obesity-associated hepatocarcinogenesis." (PMID 30523261, 2018). "Our data revealed increased GSK-3β phosphorylation in high fat diet-fed mice following TUDCA treatment, favoring a likely role of GSK-3β phosphorylation (or inactivation of GSK-3β) in the preserved mitochondrial function in high fat diet-induced obesity." (PMID 23667647, 2013).